CD34 (CD34 molecule)
Diseases named in the same sentence as CD34 in open-access papers (continued):
Sharing a sentence is not in itself a finding about the gene and the disease.
leukemia (continued). "To investigate the role of Sharp1 in leukemia-initiating potential, we first assessed the frequency of L-GMP (Lin− c-kit+ Sca1− CD34+ CD16/32+) in MLL-AF6 AML cells by flow cytometry." (PMID 29692408, 2018). "Here, we report that Nanog is significantly overexpressed in CD34+ cell populations from patients with AML and in LSCs from leukemia cell lines." (PMID 30013477, 2018). "In 1994 it was shown that leukemic cells possessing the CD34+CD38- cell-surface markers were able to initiate leukemia in severe combined immunodeficiency (SCID) mice, while CD34+ or certain CD34+CD38+ expressing cells were unable to do so." (PMID 30320108, 2018). "Our results demonstrate that Nanog is overexpressed in patient-derived CD34+ leukemia cells and in CD34+CD38- LSCs from leukemia cell lines." (PMID 30013477, 2018). "Because hematopoietic stem/progenitor cells (HSPC) are considered to be the main target for origination of leukemia and apoptosis is the key process for eliminating damaged cells, we analyzed DSB and apoptosis in CD34+ HSPC in comparison to CD34- lymphocytes." (PMID 29721197, 2018). "Nanog is overexpressed in cancer cells and in this study, we found that Nanog is overexpressed in CD34+ cells of patients with AML and in CD34+CD38- cells of leukemia cell lines." (PMID 30013477, 2018). "In this preclinical setting, we further demonstrated that a low dose of chidamide can sensitize conventional chemotherapeutics to leukemia stem cell-like cells, including CD34+CD38− KG1α cells, CD34+CD38− Kasumi cells, and primary AML stem/progenitor cells." (PMID 28814980, 2017). "Analogous results were obtained in leukemia stem-like cells sorted from Kasumi-1 cells, another human AML cell line, with 92.7±3.1% of CD34+/CD38− cells." (PMID 28518151, 2017). "Hematopoietic stem/progenitor CD34+ cells (HSPC) give rise to all types of blood cells and represent a key cellular target for origination of leukemia." (PMID 28415626, 2017). "Noted the leukemia origin of K562 cells, we also detected the expression of CKIP-1 during megakaryocytic differentiation of human CD34+ hematopoietic progenitor cells, and upregulation of CKIP-1 expression level was observed." (PMID 28404913, 2017). "In other types of leukemias, as chronic myeloid leukemia (CML), NK cells are able to kill CD34+ CML cells in the presence of intact HLA inhibitory molecules." (PMID 28404876, 2017). "An early study suggested that CD34+CD4− and CD34+CD7− cells, which make up a fraction of the leukemic cells from pediatric T-ALL patients, had leukemia-initiating properties when engrafted into NOD/SCID mice." (PMID 29034206, 2017). "Mitochondrial biogenesis has been observed during TPO-induced differentiation of CD34+ hematopoietic stem cells, PMA-induced differentiation of K562 leukemia cells and LiCl-induced differentiation of DAMI megakaryoblastic cells." (PMID 29287084, 2017). "A retrospective study involving 34 adult leukaemia patients (AML and ALL) who received TCR-αβ-depleted haploidentical HSCT with CD34+ progenitors after a myeloablative conditioning regimen showed favourable GVHD-free survival rates." (PMID 28635677, 2017). "Here we show that cordycepin reduces CD34+CD38− cells in U937 and K562 cells and induces Dkk1 expression via autocrine and paracrine regulation in leukemia and mesenchymal stromal/stem cells (MSCs)." (PMID 28266575, 2017). "MK-2206 has been shown to be able to markedly reduce the CD34+/CD7−/CD4− T-ALL subset, which has been reported to be enriched in LICs, in addition leukemia-initiating cell activity has been shown to require Cn in T-ALL." (PMID 27304189, 2016). "Here we investigated the genetic characteristics of CD7+/CD34+ and CD7+/CD34− cells from newly diagnosed human T-ALL and correlated it to the speed of leukemia development." (PMID 27191650, 2016). "CD34 and CD38 expression were detected in most B-ALL and can serve as a specific biomarker for the prognosis of this subset of leukemia." (PMID 28018598, 2016).
leukemia (continued). "Of the CD34+CD10+ and CD34−CD10+CD19+CD179a+ populations, the leukemia cell subpopulations exhibited a central tendency." (PMID 27559941, 2016). "Meanwhile, KG1a cells exhibit an LSC-like phenotype with high levels of CD34 expression (98.6%) and low levels of CD38 expression (24.6%), so it was considered as a leukemia stem-like cell line." (PMID 27542251, 2016). "It has been reported that LSCs which bear the CD34+CD38– immunophenotype play the major role for initiation of leukemia, drug resistance, and recurrence of leukemia, and are related to minimal residual disease (MRD)." (PMID 27658462, 2016). "By intravenously injecting purified CD34+CD38+CD19+ or CD34+CD38−CD19+ cells from B-precursor ALL patients, they successfully demonstrated the leukemia-initiating capacity of both cell types." (PMID 28018598, 2016). "When combined, LDE225 + nilotinib reduced CD34+ CP-CML cell engraftment in NSG mice and, upon administration to EGFP+ /SCLtTA/TRE-BCR-ABL mice, the combination enhanced survival with reduced leukaemia development in secondary transplant recipients." (PMID 27157927, 2016). "In the future, it would be of great interest to study the frequency of CD34+/CD38−CD123+ cells post induction and consolidation chemotherapy as these cells may represent the highly resistant cells to chemotherapy and might be the cells that cause regrowth of leukemia and thus relapse of the disease." (PMID 27465508, 2016). "To further investigate the specificity of the CD3CAR NK-92 cells in targeting primary leukemia patient samples, we considered a T-ALL patient sample expressing only a small subset of CD3+ T-cells, with a predominantly CD34+ CD3- tumor burden." (PMID 27494836, 2016). "This corroborated the significant differences between serum exosome levels of miR-150, -155, and -1246 in leukemia engrafted mice and levels in baseline NSG or in human CD34+ cell-engrafted controls." (PMID 26067326, 2015). "We have recently shown that CD34+/CD38- AML cells are in a dormant state and are more refractory to the anti-leukemia agent, cytarabine, than mature CD34+/CD38+ AML cells." (PMID 25955299, 2015). "It has been demonstrated that CD34, CD133, CD44, and ALDH1 mark CSCs in leukemia and some solid tumors." (PMID 26273420, 2015). "Higher BM Robo4 expression were positively associated with the expression of HLA-DR (P<0.0001), CD13 (P = 0.0417), CD34 (P = 0.0009) and CD56 (P = 0.039) on the leukemia cells." (PMID 25794001, 2015). "We then stained MLL-AF9 primary leukemia bone marrow with antibodies against Flt3, lineage markers (Lin), Sca1, Kit, CD24, CD34, and CD16/CD32, and analyzed the samples by FACS." (PMID 25517911, 2014). "Nilotinib particularly targets CD34+CD38− stem cells and MDR leukemia cells, and effectively enhances the efficacy of chemotherapeutic drugs by blocking the efflux function of ABC transporters." (PMID 24651611, 2014). "On the other hand, in more severely immune-compromised mouse models, CD34+CD38+ and CD34-negative compartments were also found to contain leukemia initiating cells." (PMID 25244440, 2014). "Taken together, these data suggest that nilotinib particularly targets CD34+CD38− stem cells and MDR leukemia cells, and effectively enhances the efficacy of chemotherapeutic drugs by blocking the efflux function of ABC transporters." (PMID 24651611, 2014). "In contrary, other investigators have shown that CD34+CD19+CD38± cells sorted from patients’ BM were able to initiate leukemia in NSG mice, had self-renewal properties, and resulted in lethal CD19+ leukemia in the host." (PMID 24847444, 2014). "CD34 and CD38 were used as markers in the original studies of leukemia stem cells which were first identified at the beginning of research." (PMID 24689055, 2014). "The CD34+CD38+ and CD34- compartments have been shown to contain leukemia initiating cells (also in this paper)." (PMID 25244440, 2014).
leukemia (continued). "Each leukemia sample in our dataset belongs to one of eight different subtypes of leukemia: hyperdiploid, TCF3-PBX1, ETV6-RUNX1, MLL, Ph, Hypo, T-ALL and Other, or to non-leukemia sample types CD10CD19 and CD34." (PMID 24932011, 2014). "The engrafted leukaemia revealed the presence of early CD34+CD19+CD10−, intermediate CD34+CD19+CD10+ and late CD34−CD19+CD10+ ALL progenitors that had the capacity to proliferate in vivo." (PMID 23872705, 2013). "qRT-PCR was performed for each of the 14 new genes, as well as for 5 standard control genes (GAPDH, ACTB, TBP, HPRT1, ABL1), on cDNA from a panel of 14 leukemia samples (10 AML, 4 ALL) plus one CD34+ cord blood sample (using equal amounts of RNA)." (PMID 24069164, 2013). "LSCs are often phenotypically defined as simply the CD34+ leukemia cells or, more recently, the more enriched CD34+CD38− subset, but even the CD34+CD38− cells are a heterogeneous population of which the LSCs constitute only a fraction." (PMID 23651669, 2013). "MiR-150 expression was significantly lower in CD34+ sorted progenitor cells from healthy individuals and in adult BC CML and AML leukemia samples as compared to average miR-150 expression in unsorted NBM." (PMID 24086639, 2013). "CLO-TOR was pro-apoptotic in an AML patient blast subset (CD34+/CD38−/CD123+), which is enriched in putative leukemia initiating cells (LICs)." (PMID 23271044, 2012). "Acute myeloid leukaemia patients with hypermethylation of any SFRP gene as a whole had higher frequency of CD19 (P=0.0004), CD7 (P=0.0144), and CD34 expression (P=0.012), but had lower frequency of CD14 expression (P=0.0395) on the leukaemia cells." (PMID 22095226, 2011). "In present study, we found Icaritin, a compound purified from traditional herb medicine exhibited a potent anti-leukemia activities towards established CML cell line-K562 and primary bone marrow cells (including CD34+ cells) from CML patients." (PMID 21887305, 2011). "The level of miR-92a expression in fresh leukemia cells was highly variable compared with PBMNC, but significantly lower compared with CD34-positive cells obtained from healthy volunteers." (PMID 21182798, 2010). "Moreover, serial transplantation of CD34+/CD38− leukemia cells demonstrated a capacity for self-renewal, offering strong support that the CD34+/CD38− subpopulation encompasses leukemia cells with stem cell–like properties." (PMID 41295979, 2026). "Instead, the results favor a nonhierarchical relationship between the leukemia stem cell compartment (CD34+/CD38−) and other cell states, such that the mathematical modeling predicts that it is possible to access all cell states from any cell state." (PMID 41295979, 2026). "Healthy non‐leukemic CD34+ cells and other leukemia cell lines with wild‐type FLT3 exhibited no induction of AXL protein levels when treated with FLT3 TKI, even with differing basal AXL levels across the different cells." (PMID 39395205, 2025). "Cells inferred to be otherwise healthy CD34+CD38– stem/progenitor cells lacking the leukemic phenotype but with potential for leukemia initiation, termed “pre-LSCs” have been identified in patients with de novo AML." (PMID 41424935, 2025). "A significant reduction in BM cellularity, leukemia burden in PB and leukemia, as well as LSC (CD34+CD38− and CD34+CD38+ cells) burden was observed in end-study organs of CLL1CART-treated mice compared to negative controls after sequential treatment with CLL1CART." (PMID 40268927, 2025). "We showed that PL exhibits in vitro cytotoxicity against AML cells, including CD34+ leukaemia-propagating cells, but not healthy haematopoietic progenitors, suggesting anti-leukaemia selectivity." (PMID 38503729, 2024). "Importantly, PL reduced the CD34 + AML stem/progenitor cell subpopulation in KG-1a cells and hindered leukaemia development in a mouse xenograft model, highlighting its potential to target LSCs." (PMID 38503729, 2024).
leukemia (continued). "Furthermore, these WT1-CTLs effectively killed AML cells with a CD34+/CD38− immunophenotype, a cell compartment which is classically enriched with leukemia-initiating cells [(LICs) or leukemic stem cells (LSCs)]." (PMID 39711535, 2024). "It was shown that this leukemic stem cell (LSC) population is CD34+CD38- and has a strong ability to reinitiate the same leukemia in mice, whereas CD34+CD38+ cells do not have such an ability." (PMID 38790277, 2024). "CD34+ areas had higher CD74 and CD68 expression as compared with CD34− areas, while this pattern was absent in healthy tissues, confirming a leukemia-specific proximity of RECs and CD34+ cells." (PMID 38582086, 2024). "Dick and coworkers revealed that only the leukemic cells expressing CD34+/CD38− markers, like normal adult hematopoietic stem cells, could induce hematopoietic malignancy and are called leukemia-initiating cells or LSCs." (PMID 37692500, 2024). "Strikingly, rLO was able to promote cell death by necrosis in CD34 + hematopoietic cells of leukemia patients, but healthy donor cells showed neither apoptosis nor necrosis following rLO treatment." (PMID 38355518, 2024). "TCRFLT3D/Y cells rejected both CD34+ and CD34− AML in mice engrafted with primary leukemia from patients, reaching minimal residual disease-negative levels, and eliminated primary CD34+ AML leukemia-propagating cells in vivo." (PMID 37783807, 2023). "Additionally, CSCs in leukemias are often characterized by the expression of specific cell surface markers, such as CD34, CD38, and CD123, among others, which can be isolated to study CSC populations in leukemia samples." (PMID 37614497, 2023). "A CD34 SCB is particularly advantageous in patients with NMDs, where graft-versus-leukemia and associated GvHD are of no benefit." (PMID 37027103, 2023). "Unlike patient 7, this AML co-expressed CD34, a stem and progenitor marker characteristic of CD34+ AMLs47, for which CD34+ cells in contrast to CD34− cells have been shown to possess leukemia-propagating activity." (PMID 37783807, 2023). "These include MUC1 and CD44 for breast cancer, CD44 for colon cancer, or CD34 for leukemia, although one cell is not restricted to only one carrier." (PMID 37915564, 2023). "LY/Api also resulted in the notable downregulation of anti-apoptotic proteins, such as NF-κB, and Bcl-xL in CD34+CD38− leukemia cells, but not in healthy HSCs." (PMID 36984844, 2023). "A strong positive CD34 expression, indicative of hematopoietic stem cells, observed in 80% of MPAL cases, may explain why some of these leukemias can differentiate into both lymphoid and myeloid cells." (PMID 35875063, 2022). "We deepened the analysis of the apoptotic death triggered by BK124.1 into the subpopulations of CML CD34+ cells distinguished by double labeling with anti-CD34 and anti-CD38 antibodies, particularly focusing on the CML CD34+/38− cells corresponding to leukemia stem cells." (PMID 35892900, 2022). "From another study, the expression of human ether‐a‐go‐go‐related gene (hEGR) K+ channel is observed in a subpopulation (CD34+CD38–CD123high) of leukemia cells but not in normal bone marrow CD34+/CD38– HSPCs." (PMID 34786735, 2022). "For example, CD34 was reported as a marker for T-LICs in xenografts from pediatric T-ALL, whereas in adult T-ALL-derived xenografts, the CD7+CD1a− but not the CD34+ subset initiates leukemia in response to NOTCH1 activation." (PMID 36428753, 2022). "Notably, we proved that CAR.CD123-NK cells significantly eradicated CD123+ cells in all CD38+CD34−, CD38+CD34+, and CD38−CD34+ cell subsets compared to the control conditions (leukaemia alone and NT-NK cells)." (PMID 36335396, 2022). "IPO11 was detected at the protein level only in the C34+ stem cell fraction, and not in the CD34− bulk leukemia fraction of 8227 cells." (PMID 35152270, 2022).
leukemia (continued). "Contrarily, the CD34‐negative leukemias had upregulation of genes involved in cell cycle, cytoskeletal organization, positive regulation of apoptosis, protein transport, and cellular response to stress." (PMID 35271751, 2022). "Two of the patients (pAML17 and pAML21) had CD34 negative leukemia, whereas in pAML23 and pAML29, the blasts displayed a broad CD34 expression and were termed CD34 positive." (PMID 35892824, 2022). "In chronic myeloid leukemia (CML), both total and phosphorylation levels of CaMK2γ were highly increased in CD34 + /CD38− leukemia stem cells (LSCs) but not in CD34- CML cells and normal hematopoietic cells (HSCs)." (PMID 34193145, 2021). "FCM was performed to test whether BM-MSC-exos could promote the stemness of AML cells, and the results revealed that exosome treatment increased the expression levels of CD34 and CD123 in leukemia cells (P < 0.05)." (PMID 33789743, 2021). "Phenotypes of leukemia cells changed after serial transplantations, with c-Kit+Gr-1+ cells becoming the main population of GFP+ cells, accompanied by a reduction of Sca-1+, CD34+, and CD11b+ cells." (PMID 34117212, 2021). "We next explored whether CAR T cells inhibit leukemia colony formation (CFU) of CD34+ and CD34− BM-derived AML cells." (PMID 34750374, 2021). "Functionally, authors showed a significant effect of STM2457 in reducing clonogenic potential and inducing apoptosis in human and mouse AML model without affecting normal human cord blood (CD34+/HSPCs) and non-leukaemia (HPC7) hematopoietic cells." (PMID 34207299, 2021). "Finally, as in the CD133-negative leukemia cells, the PROM1 promoter was marked by H3K27me3 in CD34− FBM and FL, consistent with its repression by PRC2." (PMID 32242051, 2021). "The study could have been more informative if we could profile KIAA0125 expression of healthy CD34 + CD38- HSCs and more mature progenitors (CD34 + CD38- and CD34-CD117+, respectively) and compare those with leukemia blasts." (PMID 33225420, 2021). "Besides, the high expression and activation of viral integration site 1 (EVI1) in CD34+CD38– stem cells leads to increase self-renewal capacity, leukemia development and the disease progression to BP." (PMID 34922630, 2021). "(A) Basal respiration in intact cells – ‘PBMC’ (age-matched to the primary leukemia samples); ‘BMHealthy’ (bone marrow mononuclear cells); ‘CD34+’ (pure CD34+ cells not exposed to growth factors); ‘P." (PMID 34132194, 2021). "Unlike the expression of IL-10R on leukemia cell lines or primary leukemia cells, the expression of IL-10A or IL-10RB on CD34+ UCB cells was much lower." (PMID 34392305, 2021). "Blast cells from KMT2Ar leukemia patients typically display a myelomonocytic phenotype and no expression of CD34 in contrast to the most non-KMT2Ar leukemia patients." (PMID 32517300, 2020). "Thus, we employed ALDH1 and side population in CSCs of various cancer types and CD34 and CD133 in CSCs of leukemia 27 to ascertain the stemness of resistant DLBCL cells." (PMID 32194860, 2020). "We tested the effect of this compound on MLL-rearranged (MV4;11, MOLM13) and non-MLL-rearranged leukemia cell lines (HL-60, K562, Kasumi-1), as well as on normal CD34+ cord blood cells." (PMID 32398749, 2020). "Importantly, immunohistochemical examination confirmed infiltration of CD34+/CD38+ blasts in the spleen, consistent with aggressive leukemia development in vivo." (PMID 33163905, 2020). "NKG2D-ligands are not expressed on healthy T cells or freshly isolated CD34+ stem cells and therefore represent an alternative CAR T cell target for the treatment of these high risk leukemias." (PMID 33384686, 2020). "CD34+ acute myeloid leukemia stem cells are defined as CD38-negative and CD34-positive; although these subpopulations are rare, they are mainly responsible for maintaining leukemia development." (PMID 32586050, 2020).